FAP (fibroblast activation protein alpha)
Diseases named in the same sentence as FAP in open-access papers (continued):
Sharing a sentence is not in itself a finding about the gene and the disease.
cancer (continued). "Another example is the Fibroblast Activation Protein (FAP)-targeted radionuclide therapy such as lutetium-177-FAPi which targets FAP-expressing Cancer-Associated Fibroblasts (CAFs), stroma cells from the TME endowed mainly with protumoral and immunosuppressive properties." (PMID 38433837, 2024). "FAP overexpression is associated with poor cancer prognosis and is, therefore, an excellent biomarker for cancer and an important target for diagnosis and therapeutic applications in nuclear medicine." (PMID 39076612, 2024). "FAP is highly expressed in cancer-associated fibroblasts (CAFs) and critical in PDAC." (PMID 39410042, 2024). "FAP-targeted radiopharmaceuticals derived from small molecules or peptides are currently the most promising diagnostic markers in nuclear medicine, such as in positron emission tomography and single photon emission computed tomography and cancer treatment." (PMID 39660049, 2024). "Consequently, CAF populations with elevated FAP expression are linked to reduced survival rates and more aggressive cancer phenotypes." (PMID 38606999, 2024). "However, FAP is significantly and detectably expressed by cancer-associated fibroblasts (CAFs), promoting tumorigenesis and malignant behavior." (PMID 39338305, 2024). "However, only collagen was associated with altered CD8+ T cell infiltration, despite previous RNA-based reports that FAP is associated with an immune suppressive environment We next expanded our search to identify altered pathways in marker-high cancers." (PMID 39335130, 2024). "Croizer H has expounded on the malleability of FAP+ cancer-associated fibroblasts (CAFs) and their intricate crosstalk with immune cells, identifying a spectrum of 10 spatially orchestrated FAP+ CAF clusters associated with cellular modules, designated as EcoCellTypes (ECTs)." (PMID 39439806, 2024). "FAP is a serine protease that is overexpressed in cancer-associated fibroblasts (CAFs)." (PMID 37345192, 2023). "Subsequently, we tried to figure out the association between FAP mRNA and cancer stages." (PMID 37325617, 2023). "The ROC curve reflects the diagnostic efficacy of FAP expression for each type of cancer." (PMID 37490719, 2023). "Furthermore, FAP is significantly correlated with the infiltration of cancer-associated fibroblasts, macrophages, myeloid dendritic cells, as well as endothelia cells." (PMID 37166418, 2023). "For a long time, FAPα was considered exclusively a marker of cancer-associated fibroblasts." (PMID 38136590, 2023). "Prior studies suggest that polarization of macrophages toward this SPP1+ state is a result of TME properties, including oxygen tension, the presence of FAP+ cancer-associated fibroblasts, and ECM composition, consistent with our pathway analysis of SPP1+ macrophages." (PMID 38036590, 2023). "In addition, cell identities of clusters were correctly identified even when the key canonical marker genes (e.g., PDPN and FAP of cancer-associated fibroblast) were out of the input gene list." (PMID 37924118, 2023). "Moreover, in cancer-associated studies, FAP and DPP-4 have been shown to form heterodimers that form pseudopod-like complexes on the cell surface, providing conditions for subsequent cell migration." (PMID 37006278, 2023). "Investigating the differential expression of FAP in diverse cancer types and its implications for patient survival would yield valuable insights into the underlying biology and clinical significance of FAP in cancer." (PMID 37490719, 2023). "Fibroblast activation protein (FAP) is overexpressed by cancer-associated fibroblasts." (PMID 35997853, 2023). "However, research of the therapeutic potential of FAP is limited both by legal restraints when working in vivo and by the difficulty of obtaining standardized primary cultures of FAP-positive cancer-associated fibroblasts due to their high heterogeneity." (PMID 37509656, 2023).
cancer (continued). "Furthermore, we also analyzed the association between FAP expression and pathological stage for each type of cancer." (PMID 37490719, 2023). "In addition to M2-like TAMs, fibroblast activation protein-α (FAP)+ cancer-associated fibroblasts (CAFs) serve as the target of engineered exosomes to remodel TME." (PMID 36922504, 2023). "FAP overexpression in CAFs and cancer cells is also associated with a worse prognosis." (PMID 37727209, 2023). "Fibroblast activation protein-α (FAP-α) is a transmembrane serine protease that is attracting significant interest as it is expressed by a subgroup of cancer-associated fibroblasts that play a role in immune suppression and cancer metastasis." (PMID 36937451, 2023). "Furthermore, our study confirmed that high FAP expression is associated with a poorer prognosis in most cancers." (PMID 37490719, 2023). "FAP and PDGFRα are known as cancer-associated fibroblasts markers." (PMID 37958844, 2023). "Fibroblast activation protein (FAP)–α is highly expressed in cancer-associated fibroblasts in most epithelial cancers but is weakly expressed in normal tissues, making it an attractive target for cancer imaging and therapy." (PMID 37142301, 2023). "The role of nuclear FAPα is still unclear, but it could be linked to the activation of several mechanisms underlying cancer cell invasion and migration." (PMID 36982752, 2023). "Overall, overexpression of FAP has been associated with poor prognosis in multiple types of cancer." (PMID 38313431, 2023). "Additionally, a recent study demonstrated the diagnostic precision of [68Ga]Ga-FAP-2286 in various types of cancer, including HNC." (PMID 38026901, 2023). "Another study found aberrant overexpression of FAP on cancer-associated fibroblasts, suggesting that FAP and Nectin4 could serve as promising targets for safe and effective CAR-T therapy in malignant solid tumors." (PMID 38063927, 2023). "FAP is expressed in reactive fibroblasts in the context of chronic inflammation and liver cirrhosis, in healing wounds, during embryonic development, and in cancer‐associated fibroblasts (CAFs) in many types of cancers in humans." (PMID 35818720, 2022). "In contrast, cancer-associated fibroblasts are specifically characterized by the expression of FAP." (PMID 36051919, 2022). "In addition to its role in diagnostic imaging, reliable expression in cancer and wide absence in other tissues potentially qualify FAP as a theranostic molecular target." (PMID 34957527, 2022). "Their full role remains unclear, but FAP expressing cancer associated fibroblasts (CAFs) have been found to relate to a poor prognosis with worse survival rates in breast, colorectal, pancreatic, and non-small cell lung cancer (NSCLC)." (PMID 35359378, 2022). "This illustrates the need for further investigation into underlying mechanisms and suggests that FAP might offer an attractive target to locally modulate immune responses in cancer." (PMID 35479076, 2022). "Fibroblast-activation protein (FAP) is a membrane-anchored peptidase that is highly expressed in cancer-associated fibroblasts (CAFs) in >90% of epithelial tumours, including CRC, and contributes to disease progression and worsening prognosis in various cancers." (PMID 36698416, 2022). "The abundant expression of FAP in cancer and stromal cells, and particularly in CAFs, has been implicated in different cancer-related signaling pathways, thereby contributing to cancer progression, invasion, migration, metastasis, immunosuppression, and resistance to treatment." (PMID 36263225, 2022). "Moreover, cancer-associated fibroblasts can be destroyed by using fibroblast activation protein (FAP)-directed CAR-T cells." (PMID 35453554, 2022). "Given that FAP overexpression may be associated to the inhibition of ferroptosis in cancer cells, we speculate that FAP+ CAFs may inhibit ferroptosis through the effects of GGT5 on GSH and ROS levels, but no related reports have been published." (PMID 36422541, 2022).
cancer (continued). "Studies indicate that FAP+ TAFs produce CXCL12/SDF-1 that may be responsible for coating cancer cells and causing T-cell exclusion." (PMID 35814453, 2022). "FAP-targeted radiopharmaceutical therapy might deliver therapeutic radioisotopes to cancer-associated fibroblasts." (PMID 34593598, 2022). "FAP is a marker expressed on cancer-associated fibroblasts in human solid tumors." (PMID 35911706, 2022). "Thus, FAP expressed by cancer-associated fibroblasts is an attractive diagnostic and therapeutic target." (PMID 34740953, 2022). "We analyzed the following stromal markers that reflect different stromal cell populations: CD8 (cytotoxic T cells), CD163 (cancer-associated macrophages), fibroblast activation protein (FAP, for cancer-associated fibroblasts), and alpha-smooth muscle actin (SMA, for smooth muscle cells)." (PMID 36874403, 2022). "Moreover, fibroblast activation protein (FAP) is a proline selective serine protease that is overexpressed in various cancers and associated with worse prognosis." (PMID 35406721, 2022). "In addition, differential gene expression analysis showed that fibroblast-associated genes FSP1 and FAP are upregulated in fibroblast primary cultures in comparison with canine cancer cells lines." (PMID 34903806, 2021). "FAP has been linked to worse prognosis and therapy resistance in several cancers." (PMID 34525114, 2021). "The FAP-targeting Bispecific T cell engager (FBiTE) gene has been engineered into the oncolytic adenovirus ICO15K to improve the antitumoral effects by retargeting T cells to cancer-associated fibroblasts." (PMID 34316705, 2021). "Furthermore, collagen-rich stroma was associated with prolonged cancer-specific survival compared with α-SMA- or FAP-rich stroma." (PMID 33562096, 2021). "Therefore, targeting FAP-positive cancer-associated fibroblasts with anti-FAP BiTEs secreted from CAR T cells would be within the realm of possibility." (PMID 34177890, 2021). "FAP combined with CD45 is used to label a subgroup of cancer-associated macrophages." (PMID 33614646, 2021). "Although there is no single marker for CAFs, targeting an activated subpopulation like FAP+ CAFs may render cancer cells susceptible to immune invasion and to diverse immunotherapies." (PMID 33499238, 2021). "Recently, molecular imaging probes targeting fibroblast activation protein α (FAP), which is overexpressed in a variety of cancer-associated fibroblasts, have become available and might constitute a feasible alternative to FDG PET/CT." (PMID 34050405, 2021). "FAP-expressing stromal cells in the perivascular niche are surrounded by fibrillar extracellular matrix proteins, such as fibronectin, and express mesenchymal markers consistent with the phenotype of pericytes and/or cancer-associated fibroblasts." (PMID 34282761, 2021). "We investigated whether we could distinguish the two different subtypes of cancer-associated fibroblasts—anti-cancer (αSMA+/FAPα−) and pro-cancer (αSMA−/FAPα+) fibroblasts—by gene expression levels of αSMA and FAPα in bulk PDAC tumors." (PMID 32485981, 2020). "However, only recently has the concept of ‘cancer‐associated pericytes’ (CAP) been coined to designate FAP+ perivascular cells, which were phenotypically distinguishable from CAF by the absence of podoplanin." (PMID 32767843, 2020). "However, FAP is usually highly upregulated during tissue remodeling events, including cancers or cancer-associated fibroblasts (CAFs)." (PMID 33109151, 2020). "Besides cancer cells, also cancer-associated fibroblasts (CAFs), characterized by the expression of fibroblast activation protein (FAP-)α, release high amount of CCL2, leading to sustain MDSC infiltration in pMNs." (PMID 32133298, 2020). "Indeed, treatment of fresh clinical biopsies, including malignant ascites and solid prostate cancer tissue, with FAP-BiTE-encoding OV induced expression of PD-1+ on TIL with subsequent lysis of CAFs." (PMID 32664210, 2020).
cancer (continued). "Interestingly, CD8 levels were higher in responding tumors, while high levels of fibroblast activation protein alpha (FAP), a surrogate marker of cancer-associated fibroblasts related to TGF-β, was associated with resistance to immunotherapy." (PMID 32872531, 2020). "Therefore, clarifying the regulation of FAPα expression in cancer-associated fibroblasts and its associated cytokines probably provide an optional target for suppressing CRC migration." (PMID 31920487, 2019). "Furthermore, in mouse CRC model, cancer-associated fibroblasts with high FAPα expression induce resistance to immune checkpoint blockade by up-regulating C–C motif chemokine ligand 2 (CCL-2) secretion, recruiting myeloid cells, and decreasing T-cell activity." (PMID 31920487, 2019). "The high expression of the cancer-associated markers FAP and podoplanin in normal skin fibroblasts, could suggest an upregulation of some markers through serial passaging." (PMID 31068935, 2019). "The future success of FAP inhibitors may depend on the endogenous susceptibility of cancer cells to T cell mediated killing." (PMID 30726287, 2019). "Most studies demonstrated that carcinoma-associated fibroblasts (CAFs) remain the major stromal cell population participating in the epithelial-stromal interaction in the remodeled micro environment, which were mainly responsible for production of FAP-a." (PMID 31921678, 2019). "As an approach to immunogene therapy targeting stromal rich tumors, we have created a transgene-modified variant of EnAd expressing a bi-specific T-cell activator molecule (FAP-TAC) recognizing human fibroblast activating protein (FAP) on cancer associated fibroblasts (CAFs) and CD3 on T-cells." (PMID 30400822, 2018). "It is conceivable that anti-FAP treatment may alter immune defence in cancer patients, a cohort that is highly susceptible to untoward consequences of infection." (PMID 28158223, 2017). "Like CXCL14, FAP expression has been associated with cancer-associated fibroblasts." (PMID 26893359, 2016). "In addition, similar to previous findings, high expression of FAP α in fibroblasts and carcinoma cells is associated with poor clinical outcomes." (PMID 26985769, 2016). "Characteristically, activated fibroblasts express FAP and presence of FAP has been implicated in the pathology of cancers, chronic inflammatory disorders, fibrosis and other pathologies indicating possible roles for FAP in facilitating cell invasion and growth." (PMID 25852817, 2015). "Moreover, we also detected many fibroblast activation protein (FAP)-positive fibroblasts, called cancer-associated fibroblasts (CAFs), within the lymph nodes of ATL patients." (PMID 26597716, 2015). "In addition to the activation of invasiveness and/or cell cycle progression, FAP-expressing fibroblasts have a role in immune suppression and angiogenesis during the extensive desmoplastic response associated with this cancer." (PMID 26330349, 2015). "Furthermore, FAP+ matrix-induced regulatory molecules in cancer cells revealed that it is associated with an increased activation of FAK that is independent of AKT activity." (PMID 21668992, 2011). "The widespread expression of FAP has made it an attractive therapeutic target based on the underlying hypothesis that eliminating protumorigenic CAFs will disrupt the cross-talk between components of TME resulting in cancer cell death and immune infiltration." (PMID 38747612, 2024). "Interestingly, the excluded phenotype was associated with upregulation of TGFβ and high expression of markers for cancer-associated fibroblasts, such as FAP or PDPN, which could form a barrier to prevent T-cell infiltration." (PMID 39669575, 2024). "Furthermore, the administration of this FAP-BiTE-encoding OV to freshly collected clinical biopsies, such as malignant peritoneal ascites and solid prostate cancer tissue, resulted in the upregulation of PD-1 expression on TILs, followed by the destruction of CAFs." (PMID 38464532, 2024).
cancer (continued). "Notably, FAP expression has been studied in tissue such as a selective marker of carcinoma-associated fibroblasts and more generally, of activated fibroblasts in tissues undergoing remodelling of the extracellular matrix due to chronic inflammation, fibrosis or wound healing." (PMID 38297310, 2024). "In order to determine whether the fibroblasts in the 3D CRC μTs underwent the necessary change to become Cancer-associated Fibroblasts (CAFs), we estimated the expression of α-smooth muscle actin (αSMA) and Fibroblast Activation Protein α (FAPα), two specific markers used for CAF identification." (PMID 36982752, 2023). "Similarly, FAP expression in seventeen cancers was strongly linked to DSS." (PMID 37490719, 2023). "In most cancer types, higher FAP expression is associated with worse clinical outcomes, leading to the hypothesis that FAP activity is involved in cancer development, cancer cell migration, and cancer spread." (PMID 39355017, 2023). "Therefore, FAP can be considered an independent risk factor for multiple types of cancer." (PMID 37490719, 2023). "The expression of the FAP gene is found only under special conditions, such as in some mesenchymal embryonic tissues, in wounds or foci of chronic inflammation, and in some cell types within tumors, including cancer-associated fibroblasts, endothelial cells, pericytes, and cancer cells." (PMID 36825204, 2023). "Moreover, FAP could affect the survival probability of gastrointestinal cancer patients and has high diagnostic accuracy in the model of ROC analysis for the cancers." (PMID 37325617, 2023). "Recently, we could demonstrate that positron emission tomography with 68Gallium (68Ga) labeled fibroblast activation protein (FAP) inhibitors (68Ga-FAPI-PET) allows high contrast imaging of PDAC due to their prominent stroma containing FAP-positive cancer-associated fibroblasts." (PMID 37857656, 2023). "In addition, other immune cell types showed cancer-specific relation with FAP expression instead of universally association, and this may be due to the characteristic of diverse cancers as well as the particular roles of FAP in these cancers." (PMID 37166418, 2023). "Furthermore, we evaluated whether the isolated stroma has the specific character of cancer-associated cells such as CAFs, by detecting fibroblast activation protein (FAP), a known marker expressed in CAFs." (PMID 34874922, 2022). "The following search strategy was used: (“cancer associated fibroblast” OR “cancer-associated fibroblast” OR “CAF” OR “CAFs”) AND (“fibroblast activation protein” OR “fibroblast activation protein inhibitor OR “FAPi” OR “FAP”) AND (“Positron Emission Tomography” OR “PET”)." (PMID 35327325, 2022). "Moreover, FAP is frequently overexpressed in solid malignant tumors, where it is found in stromal cells, e.g., in cancer-associated fibroblasts and endothelial cells, and it is also present in premalignant and cancer cells." (PMID 33494271, 2021). "Furthermore, the expression of FAP is associated with poor prognosis in several kinds of cancer." (PMID 33777814, 2021). "Since the cancer associated fibroblasts are directly involved in the invasion of surrounding tissues and resistance to various therapies, a boosted radiation in areas with high FAP-activity might reduce the risk of recurrence from residual disease." (PMID 34830898, 2021). "The presence of FAP in cancer-associated fibroblasts in many epithelial tumors and the fact that overexpression is associated with a worse prognosis in cancer patients led to the hypothesis that FAP activity is involved in cancer development, cancer cell migration, and cancer spread." (PMID 29626120, 2018). "In addition, some biological properties of FAP such as matrix production supportive for cell motility, immune suppression, and angiogenesis during the extensive desmoplastic response associated with this cancer have been demonstrated." (PMID 26330349, 2015).